FANCM (FA complementation group M)
Diseases named in the same sentence as FANCM in open-access papers (continued):
Sharing a sentence is not in itself a finding about the gene and the disease.
cancer (continued). "The studies reviewed here not only unveil a novel function for human FANCM, but also point to this enzyme as a promising target for anti-ALT cancer therapy." (PMID 31552268, 2019). "Other notable genes that were significant in a specific cancer type included EME1 in KIRC and FANCM in BRCA." (PMID 26689913, 2015). "Therefore, as a regulator of FANCM, FANCD2 will be an excellent target candidate for the treatment of ALT cancers." (PMID 34743173, 2021). "Importantly, FANCM-BTR complex inhibition can be used to selectively suppress the growth and viability of ALT cancer cells." (PMID 31138797, 2019). "All the eight patients previously reported with biallelic FANCM PV suffered from cancers;16,17 however, none of our three patients has developed any cancer up to the fourth or fifth decade of their life." (PMID 29895858, 2019). "Recently, reports from three independent laboratories have disclosed a previously unappreciated role for FANCM in telomerase-negative human cancer cells that maintain their telomeres through the Alternative Lengthening of Telomeres (ALT) pathway." (PMID 31552268, 2019). "Lastly, FANCM seems to be an optimal target for anti-ALT cancer therapies because it is a non-essential factor in normal and telomerase-positive cells." (PMID 31552268, 2019). "Finally, inhibition of the FANCM-BTR complex represents an accessible and demonstrated therapeutic target for ALT cancers." (PMID 31138797, 2019). "Our data demonstrate that PIP-199 similarly phenocopies FANCM depletion and that further development of similar FANCM-BTR interaction inhibitors may provide an effective and selective therapeutic strategy to target ALT cancers." (PMID 31138797, 2019). "Moreover, the BTR complex localizes to telomeres and, together with FANCM and RAD52, is involved in alternative lengthening of telomeres (ALT), a recombination-dependent telomere maintenance pathway used by telomerase-negative cancers to achieve replicative immortality." (PMID 36894693, 2023).
tumor (34 papers, 2015 to 2025). "Samples with biallelic loss of FANCC or FANCI were scored as fHRP, whereas one tumor with biallelic loss of FANCM (and intact BRCA1/2) was fHRD." (PMID 36805632, 2023). "FANCM has recently been suggested as a susceptibility gene and as a tumor suppressor gene for hereditary BC." (PMID 36835452, 2023). "One tumour showed an alteration in FANCA, one tumour showed an alteration in FANCM (with a concomitant BRCA1 P/LP variant), and one tumour showed an alteration in RAD51C." (PMID 34680387, 2021). "P-value = 2x10-18 to 5x10-13), and increases in methylation in the tumor-derived DNA were present consistently over nine FANCM promoter associated probes (Δβ 2.68%; adj." (PMID 27902704, 2016). "In F12, the FANCM p.Q1701* germline mutation, deleting 2 C-terminal domains that may be involved in the ALT phenotype, is accompanied by paradoxical mutant allele loss in the tumor, suggesting perhaps a requirement for one functional FANCM allele." (PMID 32680567, 2020). "To test whether depletion of Rad52 inhibits FANCM-deficient tumor growth, we monitored tumor formation in a mouse xenograft model." (PMID 30022024, 2018). "Suppression of Rad52 expression in combination with FANCM knockout drastically reduces cell and tumor growth, suggesting a synthetic lethality interaction between these two genes, which offers a potential targeted treatment strategy for FANCM-deficient tumors with Rad52 inhibition." (PMID 30022024, 2018). "By contrast, FANCM, MRE11A and ERCC3 tumours either remained heterozygous, or lost the variant allele." (PMID 39794353, 2025). "In response to DNA damage mediated by HU and MMC, both FANCD2 mono-ubiquitination and FANCM phosphorylation were detected in tumor cells transfected with control siRNA (lanes 4, 7)." (PMID 26625197, 2016). "In response to DNA damage, FoxF1-deficient tumor cells showed significantly reduced FANCD2 monoubiquitination and FANCM phosphorylation, resulting in impaired formation of DNA repair foci." (PMID 26625197, 2016). "HT1080 tumor cells stably expressing His-Flag tagged FANCM (HF-FANCM) protein were used for co-immunoprecipitation (co-IP)." (PMID 26625197, 2016). "Two probes located in adjacent CGIs within the FANCM promoter region had a large degree of variation in tumor-derived DNA methylation." (PMID 27902704, 2016). "Another high grade infiltrating ductal tumor-derived DNA sample had a consistent increase in methylation at FANCM across 12 consecutive probes when compared with the remaining 42 tumor samples (Δβ 8.99%)." (PMID 27902704, 2016). "Significant, tumour-specific loss of heterozygosity occurs in nine genes (ATM, BAP1, BRCA1/2, BRIP1, FANCM, PALB2 and RAD51C/D)." (PMID 26689913, 2015). "FANCM participates in the DNA damage and repair pathway, being responsible for the repair of the DNA inter-strand crosslinks through homologous recombination and recently has been identified as a tumor suppressor gene." (PMID 36835452, 2023). "In addition to known driver mutations in DNMT3A and IDH1, one patient also had missense tumor specific mutations in the FANCA and FANCM genes." (PMID 36382570, 2023). "NGS and IHC analyses of the tumor revealed multiple defects in DDR genes and proteins, specifically, heterozygous truncating mutations in CHK1, FANCM, RAD50, POLD1, and FANCP; compound heterozygous truncating mutations in ARID1A; and loss of ATM and ARID1A protein by IHC." (PMID 32568634, 2020). "In a stark contrast, depletion of Rad52 in FANCM KO cells completely suppresses tumor growth." (PMID 30022024, 2018). "Interestingly, previous studies implicated various FA complex proteins, such as FANCM, MHF1, FAAP20 and FAAP24, in tumor cell survival after DNA damage." (PMID 26625197, 2016).
tumor (continued). "Our results indicated that germline truncation and missense variants in several genes were under selection in the tumour, with ATM, BRCA1, BRCA2 and RAD51C determined as significant from both truncation and missense analyses and BAP1, BRIP1, FANCM, PALB2 and RAD51D from truncation analysis alone." (PMID 26689913, 2015). "FANCM gapmers downregulated FANCM mRNA and protein levels, altered ALT activity, induced telomere dysfunction, and reduced ALT cell survival in vitro and tumor growth in vivo." (PMID 40125273, 2025). "Whole exome sequencing revealed missense mutations in the DNA-repair and chromatin-remodeling genes FANCM and SMARCD2, and a tumor-derived cell line revealed a complex karyotype suggesting chromosomal instability." (PMID 34041014, 2021). "Importantly, in vivo, mice inoculated subcutaneously with LiSa-2 cells depleted for FANCM, had no or lower tumor burden, compared with mice injected with control cells." (PMID 40125273, 2025). "FA proteins such as FANCD2 and FANCM are involved in the regulation of this balance by resolving or inhibiting the formation of telomere secondary structures to stabilize stalled replication forks and promote break-induced repair (BIR) to maintain the survival of ALT tumour cells." (PMID 35205225, 2022). "In addition, FANCM phosphorylation did not occur and FANCD2 mono-ubiquitination was significantly reduced in tumor cells transfected with FoxF1-specific siRNA (lanes 5, 8)." (PMID 26625197, 2016).
genetic disease (2 papers, 2014 to 2024). "In addition to FANCM, we further evaluated evidence for two other genes COL9A2 and DPYD that were previously implicated in other Mendelian diseases." (PMID 25078778, 2014).
kidney disease (1 paper, 2021). "Therefore, for SNPs corresponding to the FANCM gene region, quantitative analyses were performed on phenotypes related to kidney disease." (PMID 34067580, 2021).
FANCM also shares sentences with these, for which no sentence is quoted: Ewing sarcoma (3 papers); retinoblastoma (3); skin cutaneous melanoma (3); bladder cancer (2); cervical cancer (2); ependymoma (2); hypogonadism (2); liver cancer (2); mesothelioma (2); multiple myeloma (2); neuroblastoma (2); Sertoli Cell-Only Syndrome (2); adenocarcinoma (1); anaplastic large cell lymphoma (1); asthma (1); atopic dermatitis (1); atrial fibrillation and flutter (1); atrial septal defect (1); atypical teratoid rhabdoid tumor (1); biotinidase deficiency (1); blood disease (1); cervical dysplasia (1); cervical tumor (1); Chiari malformation (1); colon cancer (1); colorectal adenoma (1); colorectal polyps (1); desmoid tumor (1); diffuse astrocytoma (1); dysplasia (1).
A further 33 diseases each share a sentence with FANCM in 1 paper.